CD4 (CD4 molecule)
Diseases named in the same sentence as CD4 in open-access papers (continued):
Sharing a sentence is not in itself a finding about the gene and the disease.
autoimmune disease (continued). "HLA class II tetramers have been used for more than a decade to identify antigen-specific CD4 T cells in peripheral blood for a wide variety of epitopes, including analyses in human autoimmune disease." (PMID 24844227, 2014). "Previous studies in several autoimmune diseases have demonstrated a significant role for a specific subset of CD4+ T cells termed effector memory T (TEM) cells." (PMID 25352848, 2014). "In organ-specific T cell-mediated autoimmune disorders, such as T1D, CD4+ and CD8+ T lymphocytes are the major players in the destruction of pancreatic beta cells." (PMID 25333705, 2014). "Our results demonstrated that L31/CD4-/- mice replicated many clinical aspects of this complex human autoimmune disease, including both sensory and motor deficits, and a temporal course of an acute onset and a stable progression." (PMID 24401681, 2014). "Specifically, it has become increasingly clear that pathogenesis of MS and EAE expands far beyond the idea of a solely CD4+ T-cell-mediated autoimmune disease." (PMID 25374694, 2014). "RA is a T cell mediated autoimmune disease, and CD4+ T cells play an important role in the process of RA." (PMID 25548591, 2014). "It has also been reported that inhibiting the IL-12 signaling pathway attenuates CD4+ T-cell-mediated autoimmune diseases, including experimental allergic encephalomyelitis." (PMID 25120564, 2014). "Among these CD4+ T-cell subsets, the IL-23-dependent IL-17-producing CD4+ helper T cells play a pivotal role in autoimmune disease." (PMID 24688790, 2014). "EAE is a CD4+ T cell–mediated autoimmune disease characterized by perivascular CD4+ T cell and mononuclear cell inflammation, with subsequent primary demyelination of axonal tracks in the CNS that provokes progressive hind-limb paralysis." (PMID 24727978, 2014). "Th17 is another subset of CD4 T cells that produce IL-17, a pro-inflammatory cytokine involved in the autoimmune diseases and other immunopathology." (PMID 24788117, 2014). "CD4+CD38+DR+ percentage was significantly higher in autoimmune disease controls as compared with thrombotic APS patients." (PMID 24982803, 2014). "Many studies have shown a reciprocal relationship between Th17 and regulatory T cells, and autoimmune diseases often result from an imbalance in these CD4+ T cell subsets." (PMID 24882950, 2014). "It is well-known that HIV patients with a CD4+ cell count less than 200 cells/mm3 are likely to develop PCP and that the most common identifiable risk factor for developing PCP in patients with autoimmune disease or malignancy is the use of glucocorticoids." (PMID 24495443, 2014). "It is well-known that HIV patients with a CD4+ cell counts less than 200 cells/mm3 are likely to develop PCP, and the most common identifiable risk factor for developing PCP in patients with autoimmune disease or malignancy is glucocorticoid use." (PMID 24495443, 2014). "The incidence of most autoimmune diseases increases with age, and premature CD4+ T cell aging has been reported in several autoimmune diseases." (PMID 24586733, 2014). "Atherosclerosis is believed to belong to autoimmune diseases, based principally on the evidence of CD4 T cells-mediated immune responses to self-antigens such as HSP-60 and oxidized low density lipoprotein (OxLDL)." (PMID 25269085, 2014). "Due to their relevance in autoimmune diseases we also studied the frequencies of regulatory T cells (Treg defined as CD3+CD127−CD25+CD4+) and observed a trend towards decrease in Treg subpopulation of T cells in all but one donor (eight out of nine)." (PMID 25541968, 2014). "Given that RA is an autoimmune disease characterized by the chronic activity of inflammatory cells, we performed the functional enrichment analysis of the CD4+ T cell modules over GO terms related to the immune system." (PMID 24959711, 2014).
autoimmune disease (continued). "Lymphocytes with regulatory properties such as Foxp3+CD25+CD4+ regulatory T cells are of crucial interest as they play essential role in maintaining peripheral tolerance preventing autoimmune diseases." (PMID 25541968, 2014). "Foxp3 transduction of naive CD4+ T cells can convert these cells into functional Foxp3+ Treg cells that prevent or suppress the development of a number of autoimmune diseases in animals." (PMID 25152867, 2014). "The potential of CD4+Foxp3+ Treg to influence the course of immune-mediated disorders and autoimmune diseases has become a major focus of advanced cellular immunotherapy." (PMID 23446139, 2013). "Their unique capacity to prevent autoimmunity renders CD4+Foxp3+ Treg an attractive tool for the treatment and modulation of autoimmune diseases." (PMID 23446139, 2013). "Multiple sclerosis is an autoimmune disease characterized by recurrent episodes of demyelination and axonal injury mediated primarily by CD4-positive T-helper cells with a proinflammatory Th1 phenotype, macrophages, and soluble mediators of inflammation." (PMID 24174971, 2013). "Because CD4+ T cells play an essential role in the development of autoimmune diseases, we further measured the production of IL-22 by purified CD4+ T cells." (PMID 23527071, 2013). "Tissue destruction in autoimmune disease is likely to be mediated by both CD4+ and CD8+ effector T cells, through a variety of functions including release of proteases such as GrB." (PMID 23382885, 2013). "CD4+CD25+ Tregs were important in the prevention of autoimmune diseases and were found to express high levels of Foxp3." (PMID 23781248, 2013). "CXCL10 is a powerful chemo-attractant for both CD4+ and CD8+ T cells to the site of inflammation, and is expressed in various Th1 type inflammatory diseases, and has also been implicated in autoimmune disease." (PMID 24134207, 2013). "While a recent study reported that also the abrogation of TGF-β signalling in CD11c+ cells leads to the development of autoimmune disease, this seems unlikely in our system since recombination in CD4+ CD11c+ cells was very rare." (PMID 24115907, 2013). "Endowed with highly suppressive machinery, it is now well established that CD4+Foxp3+ Treg cells regulate a diverse array of immune responses ranging from autoimmune disease, allergies, and transplant rejection, to infections and cancers." (PMID 23874336, 2013). "Both CCR6 and CXCR3 play an important role in the recruitment of CD4+ T cells in many autoimmune diseases." (PMID 24223818, 2013). "Alterations of circulating CXCR5 + CD4+ T cells have been described in patients with various autoimmune diseases, such as Sjögren’s syndrome, juvenile dermatomyositis, autoimmune thyroid disease and rheumatoid arthritis." (PMID 24069401, 2013). "Depletion of CD25+CD4+ Treg cells, which constitute 5%–10% of CD4+ T cells, produces autoimmune diseases such as inflammatory bowel disease in normal mice." (PMID 23983678, 2013). "CD4 + CD28null T-lymphocytes have been described as being antigen-specific cells against chronic viral antigens, mainly in some autoimmune diseases." (PMID 23675374, 2013). "IL-21 is produced by NKT and CD4+ T cells and plays an important role in the development of autoimmune diseases and is confirmed as a potent antitumor agent in animal models." (PMID 23741351, 2013). "The overlap between genomic regions associated with many autoimmune diseases and VDR binding in primary CD4+ cells strongly suggests a role for vitamin D in many of these diseases, as already seen for MCLs and LCLs." (PMID 23849224, 2013). "Autoimmune diseases in NOD mice share many similarities to the comparable human diseases, including the presence of organ-specific autoantibodies, autoreactive CD4+ and CD8+ T cells, and genomic synteny of susceptibility loci." (PMID 23850635, 2013).
autoimmune disease (continued). "CD4+Foxp3+ T regulatory (Treg) cells control many facets of immune responses ranging from autoimmune diseases, to inflammatory conditions, and cancer in an attempt to maintain immune homeostasis." (PMID 23874336, 2013). "The current paradigm describes MS as an autoimmune disease mediated by CD4+ myelin-reactive T cells that gain access to the CNS and initiate a proinflammatory response leading to the destruction of the myelin sheath by multiple mechanisms." (PMID 23840675, 2013). "In general, our finding of elevated CD4+CD25+CD127− T-cells in long-lasting T1D provides another evidence for lack of uniform quantitative pattern of Treg cells in the course of autoimmune diseases." (PMID 24348676, 2013). "IL-23 induces differentiation of IL-17-producing CD4+ helper T cells (TH17) and CD4+CD25+Foxp3+ regulatory T cells (Tregs) that favor the development of chronic infection and autoimmune diseases under pathogenic conditions." (PMID 23967307, 2013). "An increased level of IL-16 mRNA and protein was observed in patients with inflammatory or autoimmune diseases, and the high expression of IL-16 mRNA correlated with increased numbers of CD4+ cells in acute skin lesions." (PMID 24288444, 2013). "More recently, another pivotal subset of CD4+ T cells (Treg cells), which have been related to control immune tolerance and subsequent autoimmune diseases, were also found to be important in suppressing allergic responses." (PMID 22792275, 2012). "Multiple sclerosis (MS) and its animal model, experimental autoimmune encephalomyelitis (EAE), are autoimmune diseases mediated by myelin-reactive CD4+ T cells targeting myelin-producing cells of the CNS." (PMID 23077616, 2012). "The search for a Treg cells-specific molecular marker has revealed that the majority, if not all, of these cells constitutively express the CD25 molecule and depletion of CD25+CD4+ T cells spontaneously evokes autoimmune disease." (PMID 22844430, 2012). "RA is a proinflammatory autoimmune disease attributed to failure of both CD4+CD25+ regulatory T (Tr) and CD8+CD28− suppressor T (Ts) cells to control autoreactive CD4+CD28+ Th1 and autoantibody-producing B cells." (PMID 23133752, 2012). "On the other hand, CD25+CD4+ regulatory T cells suppress immune responses and are believed to play roles in preventing autoimmune diseases." (PMID 22675381, 2012). "Intriguingly, the subpopulation of CD4+CD8+ double positive T-lymphocytes appearing in the damaged brain and spleen post HI, has in the human setting been linked to different autoimmune diseases." (PMID 22567156, 2012). "Th17, a new CD4+ T cell lineage that preferentially produces IL-17, has been described to be involved in various autoimmune diseases." (PMID 23236476, 2012). "In this study, autoimmune diseases were induced in rats by thymectomy and irradiation; however the xenograft transfer of CD4+ T cells from normal rats can abrogate the autoimmune responses." (PMID 22481922, 2012). "Treg, Th9 and Th17 cells have been shown to be important CD4 T cell subsets in human autoimmune diseases, including rheumatoid arthritis and multiple sclerosis." (PMID 23148845, 2012). "Putative CD4 T cell epitopes of established antigens involved in autoimmune diseases that share similarity with M.tuberculosis proteins." (PMID 22435930, 2012). "A unique subset of CD4+ T cells that lack the costimulatory molecule CD28 expand in patients with autoimmune diseases, such as RA, Wegener's granulomatosis, dermatomyositis and polymyositis, multiple sclerosis, and IBD." (PMID 21473750, 2011). "IL-17 producing CD4 T cells, namely Th17 cells are well known that participates in the pathogenesis of various organ-specific autoimmune diseases, such as inflammatory bowel disease and rheumatoid arthritis." (PMID 22171643, 2011). "Recently, growing evidence has unveiled the importance of OX40 signals in the accumulation of effector CD4+ T cells at inflammation sites in mouse models of autoimmune diseases." (PMID 22171643, 2011).
autoimmune disease (continued). "We showed that autoimmune gastritis induced by adoptive transfer of H/Kα−/− CD4+ T cells represented an excellent disease model for the dissection of autoimmune response and the design of interventionary therapies for autoimmune diseases." (PMID 22096532, 2011). "Experimental autoimmune uveoretinitis, for example, is a Th1-type autoimmune disease, and the disease is characterized by macrophage and CD4 T-cell infiltration together with high levels of IFN-γ and TNF-α production." (PMID 21738388, 2011). "Considering that autoimmune disease pathogenesis invariably involves the participation of CD4+ T cells, it is likely that blockade of IL-7Rα signaling will be an efficient treatment in a wide spectrum of autoimmune and inflammatory disorders." (PMID 22102903, 2011). "In this study, we employed the label-free approach to identify differently expressed proteins in CD4+ T cells, an important population involved in various autoimmune diseases, between active VKH patients and normal controls." (PMID 21297967, 2011). "Apart from a shift in the Th1/Th2 balance, a new T cell subset (Th17 cells), the primary CD4+ cells producing IL-17, is often regarded as the principal instigator of autoimmune disorders." (PMID 22039505, 2011). "IFN- γ, a prototypic proinflammatory cytokine produced by several different cell types, including the Th1 subset of CD4(+) T cells, plays an important role in inflammation and autoimmune diseases." (PMID 21943174, 2011). "In inflammatory diseases and autoimmune diseases, CD4+ T cells serve as an important source of proinflammatory cytokines." (PMID 22066025, 2011). "Although the importance of IL-17-producing CD4+ T cells in the pathogenesis of autoimmune diseases is widely accepted, the signaling pathway involved in the development and maintenance of these cells only recently became clear." (PMID 19622600, 2011). "CD3+ CD4+ CD25+ T-cells are potent immunosuppressors that control or prevent the development of spontaneous autoimmune diseases and are involved in preventing intestinal IBD." (PMID 20379374, 2010). "Adoptive transfer of these CD4+CD25high regulatory T cells (Tregs) in animal models has been shown to offer protection from several autoimmune diseases." (PMID 21151941, 2010). "E-restricted CD4+ T cells are functionally effective by all measures tested, but the strong protective effect of H-2Ea against autoimmune diseases such as Type-1 diabetes suggests that E- and A-restricted repertoires are not always equivalent." (PMID 21179499, 2010). "The ratio of IFN-γ+/IL-4+ CD4+ T cells represents the balance between pro-inflammatory Th1 and anti-inflammatory Th2 cells, and is regarded an important variable in autoimmune diseases." (PMID 21179201, 2010). "Th1 and Th2 cells are two distinct CD4 T cell lineages, and they play different roles in autoimmune diseases, including MS and EAE." (PMID 21234105, 2010). "Collectively, these data suggest a scenario in which repetitive PTx treatment protects mice from development of CNS autoimmune disease through upregulation of regulatory cytokines and expansion of CD4+CD25+FoxP3+ Treg." (PMID 21209857, 2010). "At least in autoimmune diseases the immune response is mostly driven by autoreactive CD4+ T cell responses." (PMID 19738910, 2009). "Multiple sclerosis (MS) is a suspected autoimmune disease in which myelin-specific CD4+ and CD8+ T cells enter the central nervous system (CNS) and initiate an inflammatory response directed against myelin and other components of the CNS." (PMID 20182567, 2009). "Conversely, restoration of the CD4+CD25+ cell population from syngeneic normal mice effectively abrogates the development of autoimmune disease, as has treatment with in vitro expanded Tregs." (PMID 19543397, 2009). "CD4+CD25+FOXP3+ Regulatory T cells (Treg) play a central role in the immune balance to prevent autoimmune disease." (PMID 19779623, 2009).
autoimmune disease (continued). "It is evident for instance in the strong genetic link to class II MHC molecules and in the fact that experimental autoimmune diseases can often be induced by the adoptive transfer of auto-aggressive CD4+ T cells." (PMID 18350151, 2008). "Third, CD4+ effector T cells, which are likely autoreactive T cells typically observed in organ-specific autoimmune diseases, are generated in AID−/− mice." (PMID 18716662, 2008). "These transduced CD4+CD25high iTreg are able to inhibit proliferation and cytokine production in the effector T cells and the development of some experimental autoimmune diseases in animals." (PMID 19046457, 2008). "It is now well established that CD4+CD25+ regulatory T cells, which account for 5–10% of CD4+ cells in healthy mice and humans, control the development of many autoimmune diseases." (PMID 19011680, 2008). "Anti-inflammatory regulatory T cells have been found to be an important CD4 cell subpopulation for controlling the development of autoimmune disease." (PMID 18382691, 2008). "No reports have yet appeared to link increased apoptosis in the unmanipulated CD4+CD25+high T-cell fraction with respect to autoimmune disease." (PMID 17206281, 2007). "Adoptive transfer of naturally occurring or cultured polyclonal CD4+CD25+ regulatory T cells has been shown to exert potentially therapeutic effects on autoimmune diseases in many animal models." (PMID 17284325, 2007). "There is good evidence that the CD4+CD25+ T cell subset (natural T regulatory cells) can confer protection in a variety of autoimmune disease models." (PMID 17440622, 2007). "Adoptive transfer of CD4+CD25+ regulatory T cells has been shown to have therapeutic effects in animal models of autoimmune diseases." (PMID 17284325, 2007). "It has been shown in animal models that CD4+CD25+high T cells can prevent murine T1D bringing in new hope for the prevention of human autoimmune disease." (PMID 17206281, 2007). "Brown and associates found increased CD4+ T-cells and a TH1-like phenotype following intranasal quartz in New Zealand Mixed mice, a strain prone to autoimmune disease." (PMID 16396683, 2006). "The transfer of CD4+CD25- cells into nude mice resulted in autoimmune diseases; reconstitution of CD4+CD25+ cells after transfer of CD4+CD25- cells prevented the development of autoimmunity." (PMID 15679891, 2005). "Inoculation of CD4+ T cells depleted of CD25+ cells in nu/nu mice results in autoimmune diseases such as gastritis, thyroiditis and insulitis." (PMID 15743488, 2005). "In several autoimmune diseases, for example rheumatoid arthritis, the involvement of CD4+ T cells in disease induction has been suggested." (PMID 15899047, 2005). "Autoimmune diseases represent an abnormal recognition of self-antigens by activated CD4+ (helper) T lymphocytes." (PMID 15292926, 2004). "When the CD4+/CD8 + ratio is abnormal, it indicates that the immune status has been damaged, which may cause tumors and autoimmune diseases." (PMID 41040673, 2025). "It was found that these cells, which differentially express another key RA gene, TNFAIP3, could differentiate into cytotoxic CD4+ T cells, potentially contributing to the pathogenesis of autoimmune diseases." (PMID 39930543, 2025). "CD70+CD4+ T cells have been reported to increase in many autoimmune diseases, including systemic lupus erythematosus and multiple sclerosis, while CD70+ cancer-associated fibroblasts have been reported to promote proliferation of Tregs and create an environment to evade host immunity." (PMID 39846253, 2025). "Our identification of enriched T follicular helper (Tfh) and CD4+ T helper cells in type 1 AIP parallels findings from studies on other autoimmune disorders, including RA, SLE and Multiple Sclerosis, that emphasize the role of these cells in orchestrating immune responses." (PMID 39887620, 2025).